HOTAIR (HOX transcript antisense RNA)
Diseases named in the same sentence as HOTAIR in open-access papers (continued):
Sharing a sentence is not in itself a finding about the gene and the disease.
renal cell carcinoma (16 papers, 2015 to 2023). "In this review, we describe 14 widely reported human solid tumors associated with HOTAIR dysregulation, and we briefly review the recent data focusing on breast, lung, liver, gastric, and pancreatic cancer and renal cell carcinoma." (PMID 34367966, 2021). "It has been reported that LncRNA HOTAIR regulates renal cell carcinoma angiogenesis through the miR‐126/EGFL7 axis." (PMID 37904709, 2023). "In the present study, HOTAIR expression was elevated in tissues of renal cell carcinoma compared to adjacent normal tissues, and positively correlated with metastasis (P<0.05)." (PMID 28177890, 2017). "Collectively, these data suggest that HOTAIR is an important promoter in metastasis of renal cell carcinoma and also plays a dual regulatory role in chromatin state by effecting both histone metylation and demethylation at different gene loci." (PMID 28177890, 2017). "Here, the clinical significance and role of HOTAIR in renal cell carcinoma (RCC) tumorigenesis were explored." (PMID 28938586, 2017). "Renal cell carcinoma tumour xenografts with stimulated HOTAIR expression which were previously injected into mice were smaller and exhibited reduced proliferation." (PMID 27092491, 2016). "HOTAIR could sponge miR-138, miR-200c, miR-204 and miR-217 to increase several oncogenes to promote renal cell carcinoma progression, implying that HOTAIR may have different sponging potentials in different tissues." (PMID 32657763, 2020). "In addition, the expression level of HOTAIR is higher in renal cell carcinoma in comparison with normal kidney cells and a correlation has been shown between the upregulation of HOTAIR and distant metastasis in renal cell carcinoma malignancy." (PMID 31208095, 2019). "The lncRNA Hox antisense intergenic RNA (HOTAIR) has a role in metastasis in several cancers including renal cell carcinoma (RCC), in which elevated HOTAIR expression is prognostic for poor patient survival." (PMID 35597813, 2022).
Sepsis (16 papers, 2018 to 2025). Sepsis is defined as life-threatening organ dysfunction caused by a dysregulated host response to infection. "In sepsis‐induced acute kidney injury, HOTAIR can act as a molecular sponge to adsorb miR‐22, causing renal tubular epithelial cell apoptosis." (PMID 34296520, 2021). "In acute renal injury caused by sepsis, HOTAIR promotes the apoptosis of HK‐2 cells through the miR‐22/HMGB1 pathway, thereby causing kidney injury." (PMID 34296520, 2021). "lncRNA HOTAIR has been reported to mediate severe organ injury in a sepsis rat model through the miR-34a/Bcl-2 axis." (PMID 39067063, 2025). "LncRNA such as NEAT1, HOTAIR, and MALAT1 have been identified as being significantly associated with the development of sepsis." (PMID 34870560, 2021). "At present, studies of lncRNA expression in sepsis mainly focus on HOTAIR, MALAT1, NEAT1, TUG1, and UCA1." (PMID 34514170, 2021). "In cardiomyocytes of mice with LPS-induced sepsis, upregulation of lncRNA HOTAIR promotes TNF-α production by activating NF-κB, involving the p-NF-κB p65 subunit." (PMID 33024135, 2020). "In a sepsis mice model, LPS can induce the upregulation of HOTAIR in cardiomyocytes, in line with increased NF-κB activation and TNF-α production, which is reversed by HOTAIR silence." (PMID 31711545, 2019). "HOTAIR turned out to be up-regulated in cardiomyocytes derived from LPS-induced sepsis in mice and to promote the production of circulating TNF-α by activating NF-κB." (PMID 31694052, 2019). "lncRNA HOTAIR promoted the progression of sepsis, by inhibiting monocyte proliferation, while promoting monocyte apoptosis and inflammation response; this was achieved by acting as miR-211 sponge, thereby inducing IL-6R expression in CLP-induced sepsis mice model." (PMID 34055659, 2021). "Moreover, lncRNA HOTAIR also participated in sepsis-induced heart dysfunction by regulating the inflammatory response." (PMID 34055659, 2021). "Up-regulation of HOTAIR reduced apoptosis in sepsis-induced AKI." (PMID 34956235, 2021). "Previous studies have shown that HOTAIR is upregulated in sepsis models." (PMID 34514170, 2021). "For example, HOTAIR promotes TNF-α expression and aggravates myocardial damage caused by sepsis." (PMID 33204219, 2020). "Moreover, silencing of HOTAIR preserves cardiac function in mice with LPS-induced sepsis." (PMID 31694052, 2019). "For example, alterations in the levels of lncRNA HOTAIR and MALAT1 in sepsis patients were investigated." (PMID 39735547, 2024). "Increasing evidences demonstrate that lncRNAs are essential regulators of inflammatory response and potential biomarkers of sepsis, including NEAT1, HOTAIR, UCA1 and HULC." (PMID 36817490, 2023). "Previous studies have also found that lncRNA HOTAIR, NEAT1, and MALAT1 were differentially expressed in sepsis patients." (PMID 34514170, 2021). "Meanwhile, an increasing number of studies have shown that lncRNAs, such as HOTAIR and TUG1, have protective effects in the regulation of sepsis-induced AKI." (PMID 34630395, 2021). "The HOTAIR and tumor suppressor PDCD4 are upregulated in the LPS-induced sepsis model in mice." (PMID 38132140, 2023). "Moreover, lncRNA EGO and lncRNA HOTAIR myeloid-specific 1 arrived their peaks at 3 hours, while lncRNA IL7R arrived its peak at 24 hours in sepsis model, which suggested that lncRNAs could be ideal biological indicators for diagnosing and distinguishing different stages of sepsis in the future." (PMID 34630395, 2021).
acute myeloid leukemia (15 papers, 2017 to 2025). Acute myeloid leukemia (AML) is a group of neoplasms arising from precursor cells committed to the myeloid cell-line differentiation. "Another study has reported that miR-20a-5p interacts with the lncRNA HOTAIR contributing to adriamycin resistance in patients with acute myeloid leukemia." (PMID 40686703, 2025). "Studies indicate that in acute myeloid leukemia, lncRNA HOTAIR promotes myeloid differentiation by up-regulating p21." (PMID 38397131, 2024). "For example, a study showed that HOTAIR suppression promoted apoptosis and doxorubicin sensitivity in acute myeloid leukemia (AML)." (PMID 36100611, 2022). "HOTAIR modulated c-KIT expression through sponging miR-193a in acute myeloid leukemia." (PMID 28415631, 2017). "In acute myeloid leukemia (AML), Ling-Li and colleagues discovered that the expression of HOTAIR is elevated in drug-resistant K562/AO2 leukemia cell lines and bone marrow samples from patients with refractory and relapsed AML." (PMID 38887279, 2024). "HOTAIR plays an important oncogenic role in acute myeloid leukemia (AML)." (PMID 33540611, 2021). "In acute myeloid leukemia (AML), chronic lymphocytic leukemia (CLL), and multiple myeloma (MM), HOTAIR was reported to be dysregulated, and its high expression was associated with reduced survival times in AML patients." (PMID 33348573, 2020). "One of the first HOTAIR expression role in oncohematology was observed as regulating cell cycle progression during myeloid maturation in human promyelocytic leukemia cells and modulating c-KIT through expression sponging miR-193a in acute myeloid leukemia." (PMID 39450252, 2024). "Moreover, lncRNAs are reported to be useful for disease prognosis, exemplified by the lncRNA HOTAIR (HOX transcript antisense RNA), which is upregulated in acute myeloid leukemia (AML) patients." (PMID 30642353, 2019). "Interestingly, in the case of HOTAIR, it was shown to activate methylation at the PTEN locus by upregulating the expression of DNMT3b, thereby promoting resistance to adriamycin (ADM) in acute myeloid leukemia." (PMID 40149464, 2025). "For instance, lncRNA HOTAIR was shown to recruit DNMT3B to increase HOXA5 promoter methylation and silence its expression in acute myeloid leukemia (AML)." (PMID 36533073, 2022).
rheumatoid arthritis (15 papers, 2018 to 2025). A chronic, systemic autoimmune disorder characterized by inflammation in the synovial membranes and articular surfaces. "The abnormal expression of long noncoding RNA (LncRNA) HOTAIR has been associated with synovial angiogenesis in rheumatoid arthritis (RA)." (PMID 37904709, 2023). "HOTAIR directly targets miR-138 and is associated with the development of rheumatoid arthritis, because it is involved in maintaining the chondrocyte phenotype." (PMID 33540611, 2021). "In rheumatoid arthritis (RA), HOTAIR overexpression reduced the secretion of IL-23 and IL-17, and decreased the number of pro-inflammatory cells (Th17), as well as diminishing levels of IL-1β, phospho-p65, and TNF-α in cartilage." (PMID 37190068, 2023). "Different lncRNAs such as H19, HOTAIR, and linc-p21 are identified as altered in the bone inflammatory state (rheumatoid arthritis and osteoarthritis)." (PMID 37190068, 2023). "HOTAIR reduces the progression of rheumatoid arthritis by targeting miR-138 and inactivating the NF-κB pathway." (PMID 35087527, 2021). "In addition, studies have confirmed that HOTAIR and miR-138 can interact with each other to affect LPS-induced rheumatoid arthritis in vivo." (PMID 34970356, 2021). "Previous studies have demonstrated that the overexpression of HOTAIR suppressed the expression of miR‐138 during lipopolysaccharide (LPS)‐stimulation in chondrocytes and rats with rheumatoid arthritis (RA)." (PMID 33733597, 2021). "Therefore, HOTAIR could play a protective role in rheumatoid arthritis through the regulation of miR-138 expression and the NF-kB signaling pathway." (PMID 33540611, 2021). "However, the role of HOTAIR in rheumatic diseases is not well understood, with some evidence suggesting that HOTAIR has an important regulatory role in rheumatoid arthritis, and that it promotes the expression of ADAMTS-5 and matrix metalloproteinases (MMPs) in osteoarthritic chondrocytes." (PMID 32650720, 2020). "Furthermore, an investigation of lncRNA expression in rheumatoid arthritis fibroblast-like synoviocytes (RAFLS) following the administration of quercetin found, among other things, differential expression of MALAT1, HOTAIR, MEG3, CBR3-AS1, GAS5 and YIYA." (PMID 29751665, 2018). "The lncRNAs HOTAIR, lincRNA‐p21, lncRNA H19 and MALAT1 play important roles in the clinical diagnosis and progression of rheumatoid arthritis (RA)." (PMID 36607351, 2023).
gallbladder cancer (14 papers, 2014 to 2023). "To investigate the biological roles of HOTAIR and miRNA-130a in gallbladder cancer, we employed gain-of-function and loss-of-function approaches." (PMID 24953832, 2014). "Of note, also in gallbladder cancer the oncogenic activity of HOTAIR in promoting invasion and malignancy of tumor cells has been ascribed, at least in part, to its-mediated negative regulation of miR-130a." (PMID 37308974, 2023). "For instance, the most commonly known lncRNA, HOTAIR, is up-regulated in gallbladder cancer (GBC) that leads to tumor metastases through altered methylation of histone H3 lysine 27 (H3K27) and gene expression." (PMID 28404901, 2017). "The most well-known lncRNA, HOTAIR, is up-regulated in gallbladder cancer (GBC) that leads to tumor metastases through altered methylation of histone H3 lysine 27 (H3K27) and gene expression." (PMID 26974151, 2016). "Aside from miR-335 and miR-34a, miR-130a was markedly downregulated in gallbladder cancer tissues in which miRNA-130a levels were negatively correlated with HOTAIR, a trans-regulatory long noncoding RNA (lncRNA)." (PMID 26040010, 2015). "The authors reported that knockdown of HOTAIR inhibited the invasion of gallbladder cancer cells while miRNA-130a inhibitor reversed the decrease in invasiveness." (PMID 26040010, 2015). "We demonstrate that HOTAIR is a direct target of c-Myc through interaction with putative c-Myc target response element (RE) in the upstream region of HOTAIR in gallbladder cancer cells." (PMID 24953832, 2014). "A positive correlation between c-Myc and HOTAIR mRNA levels was observed in gallbladder cancer tissues." (PMID 24953832, 2014). "Our data showed that while knockdown of HOTAIR inhibited the invasiveness and proliferation of gallbladder cancer cells, miRNA-130a inhibitor reversed the effects that knockdown of HOTAIR exerted." (PMID 24953832, 2014). "We selected gallbladder cancer cell line GBC-SD as our experimental model as GBC-SD harbors a moderate expression level of HOTAIR, which makes it easier for manipulation." (PMID 24953832, 2014). "The expression levels of HOTAIR, c-Myc and miRNA-130a were examined in 65 matched pairs of gallbladder cancer tissues." (PMID 24953832, 2014). "HOTAIR expression was negatively correlated with miRNA-130a in gallbladder cancer tissues (r = -0.6398, p < 0.0001), providing evidence to the reciprocal negative regulation of HOTAIR and miRNA-130a." (PMID 24953832, 2014). "We demonstrated that knockdown of HOTAIR inhibited the invasion of gallbladder cancer cells while miRNA-130a inhibitor reversed the decrease in invasiveness." (PMID 24953832, 2014). "Next, we examined the expression level of HOTAIR with clinical characteristics in 65 gallbladder cancer tissues." (PMID 24953832, 2014). "What’s more, a positive correlation between c-Myc and HOTAIR mRNAs was observed in gallbladder cancer tissues, providing additional evidence to c-Myc’s regulation of HOTAIR." (PMID 24953832, 2014). "In gall bladder cancer, HOTAIR’s oncogenic activity requires its binding to and neutralization of miR-130a (1805–1826 bp in RefSeq NR_003716)." (PMID 25491133, 2014). "The expression level of HOTAIR was examined using real-time PCR in 65 pairs of gallbladder cancer tissues and matched adjacent normal tissues." (PMID 24953832, 2014). "Besides, in gallbladder cancer, HOTAIR was found targeted by miR-130a, a tumor-suppressive miRNA downregulated in the progression of different carcinomas." (PMID 37308974, 2023). "HOTAIR gene activation, in turn, promotes gallbladder cancer malignancy." (PMID 37308974, 2023). "For instance, HOTAIR is transcriptionally activated by the oncogene Myc through an E-box located at 1053 bp upstream of the transcription start site of the human HOTAIR gene in gallbladder cancer cells." (PMID 25491133, 2014). "We then then studied that biological function of HOTAIR and miRNA-130a in gallbladder cancer cells." (PMID 24953832, 2014).
gallbladder cancer (continued). "We then examined the expression level of HOTAIR in a series of gallbladder cancer cell lines." (PMID 24953832, 2014). "As c-Myc upregulates the expression of HOTAIR, we investigated whether a correlation exists between c-Myc and HOTAIR expression levels in gallbladder cancer tissues." (PMID 24953832, 2014). "c-Myc has been reported to be an oncoprotein and is deregulated in gallbladder cancer.Firstly, we would like to evaluate whether c-Myc regulates the expression of HOTAIR." (PMID 24953832, 2014). "HOTAIR is overexpressed in gallbladder cancer tissues compared with adjacent non-tumoral tissues, indicating that HOTAIR is frequently upregulated on GBC." (PMID 34575316, 2021).
leukemia (14 papers, 2015 to 2025). A malignant (clonal) hematologic disorder, involving hematopoietic stem cells and characterized by the presence of primitive or atypical myeloid or lymphoid cells in the bone marrow and the blood. "Then, the HOTAIR level in different leukemia-associated cell lines was determined." (PMID 31168296, 2019). "Another study also demonstrated that silencing HOTAIR inhibited cell proliferation in leukemia cells." (PMID 33941772, 2021). "Recently, HOTAIR high-expression was associated with acquired resistance to antileukemic drugs such as doxorubicin and immatinib, making this gene as a potential therapeutic target molecule that could contribute to solve a tremendous problem in leukemia chemotherapy, the drug-resistance." (PMID 30744139, 2019). "In recent years, HOTAIR, a type of lncRNA, has been demonstrated to participate in the progression of leukemia through regulating DNA methylation, as well as histones." (PMID 31168296, 2019). "HOTAIR acts as a carcinogenic lncRNA, and elevated HOTAIR was found predict the poor overall survival in patients suffering from leukemia and lymphoma." (PMID 31168296, 2019). "HOTAIR, a proliferation promotor of leukemic blast and leukemia stem cells, is one of the most consistently found in AL." (PMID 30744139, 2019). "In summary, high HOTAIR expression is closely related with a poor prognosis in patients with leukemia and lymphoma." (PMID 31480503, 2019). "In hematological malignancies, HOTAIR sustains cell growth and promotes the self-renewal of leukemia stem cells (LSCs) by epigenetic silencing of p15, and its upregulation is associated with higher peripheral leukocyte and BM blast counts, lower hemoglobin counts, and poor DFS." (PMID 38777995, 2024). "HOTAIR recruits EZH2 to the p15 promoter, inducing its H3K27me3 and silencing gene expression. p15 downregulation is associated with the enhanced self-renewal capacity of leukemia stem cells, promoting leukemogenesis." (PMID 37345170, 2023). "HOTAIR could serve as a potential biomarker for diagnosis, prognosis, and treatment of leukemia and lymphoma." (PMID 31480503, 2019). "The evaluation of lncRNAs expression in plasma samples from leukemia and multiple myeloma showed that TUG1, MALAT1, HOTAIR and GAS5 are more highly expressed in leukemia than in the control samples, and only lincRNA-p21 is upregulated in multiple myeloma." (PMID 25338714, 2015).